PI4KA (phosphatidylinositol 4-kinase alpha)
Diseases named in the same sentence as PI4KA in open-access papers (continued):
Sharing a sentence is not in itself a finding about the gene and the disease.
leukemia (continued). "Knockout of PI4KA could significantly increase the sensitivity of resistant leukemia cells to DOX by inhibiting OXPHOS." (PMID 36276647, 2022). "Importantly, inhibition of PI4KA by CEP enhanced the efficacy of chemotherapeutic agents in drug-resistant leukemia cells in vitro and in vivo." (PMID 36276647, 2022). "However, knocking out PI4KA in leukemia patients to treat refractory leukemia is difficult and impractical because of toxic side effects." (PMID 36276647, 2022). "Next, we investigated whether our in vitro findings that inhibition of PI4KA by CEP-sensitized chemotherapeutic drug-induced cell death in drug-resistant leukemia cells could be replicated in vivo." (PMID 36276647, 2022). "Moreover, cellular ATP production significantly decreased in PI4KA knockout drug-resistant leukemia cells." (PMID 36276647, 2022). "First, overexpression of PI4KA was observed in drug-resistant leukemia cell lines." (PMID 36276647, 2022). "A combination of the PI4KA inhibitor with classic chemotherapeutic agents could represent a novel therapeutic strategy for the treatment of refractory leukemia." (PMID 36276647, 2022). "Therefore, exploring the novel PI4KA role in the regulation of chemoresistance and chemotherapy sensitization may provide novel therapeutic strategies for treating leukemia." (PMID 36276647, 2022). "In this study, we demonstrated that PI4KA is involved in intrinsic chemoresistance of leukemia and leads to poor response to chemotherapeutic drugs and developed a PI4KA-targeting strategy to sensitize leukemia to adjuvant chemotherapy in proof-of-concept preclinical testing." (PMID 36276647, 2022). "Also, knockout of PI4KA could enhance the sensitivity of resistant leukemia cells to DOX in vitro and in vitro." (PMID 36276647, 2022). "OXPHOS may play an essential role in chemoresistance regulation by PI4KA in leukemia cells." (PMID 36276647, 2022). "Collectively, these findings suggested that PI4KA plays a critical role in chemoresistance via the ERK/AMPK/OXPHOS signaling pathway by regulating the production and polarization of PtdIns4P in leukemia." (PMID 36276647, 2022). "Overexpression of PI4KA upregulated OXPHOS by modulating the ERK/AMPK axis, leading to chemoresistance in leukemia." (PMID 36276647, 2022). "Taken together, these findings suggested that PI4KA controls mitochondrial function and OXPHOS to regulate drug resistance and proliferation in leukemia cells." (PMID 36276647, 2022). "We also tested the combinatorial effects of a documented direct PI4KA inhibitor GSK-A1 and DOX in resistant leukemia cells." (PMID 36276647, 2022). "It was found that in myeloid and erythroid lineage-linked leukemias, normal PI4Kα signaling is inhibited by upregulation of PI4KAP2, formerly considered a nonfunctional PI4Kα pseudogene." (PMID 37408244, 2023). "We also identified cepharanthine (CEP) as a novel PI4KA inhibitor, which could undermine the stability of the PI4KA/TTC7/FAM126 complex, enhancing the sensitivity of drug-resistant leukemia cells to chemotherapeutic drugs in vitro and in vivo." (PMID 36276647, 2022).
medulloblastoma (2 papers, 2018 to 2022). A malignant, invasive embryonal neoplasm arising from the cerebellum. "RNA interference screening identified PI4KA as a mediator of resistance to cisplatin in medulloblastoma cell lines, suggesting that PI4KA has a functional role in the chemoresistance of cancers." (PMID 36276647, 2022).
neuropathy (2 papers, 2016 to 2021). A disorder affecting the nervous system that manifests with pain, tingling, numbness, and/or muscle weakness. "Mice with a Schwann cell-specific Pi4ka deletion display neuropathy motor symptoms and severe myelination defects, with significantly reduced myelin thickness and lipid content most severely affecting phosphatidylserine and phosphatidylethanolamine, two major myelin components." (PMID 34415310, 2021).
polymicrogyria (2 papers, 2019). A developmental brain abnormality characterized by an excessive amount of small convolutions on the surface of the brain and cognitive dysfunction. "Mutations in the genes PIK3CA and PI4KA that encode phosphoinositide kinases are associated with polymicrogyria and cortical dysplasia, disorders that result in altered cerebral cortex morphology and cellular composition." (PMID 31507376, 2019).
22q11.2 deletion syndrome (1 paper, 2015). 22q11.2 deletion syndrome (DS) is a chromosomal anomaly which causes a congenital malformation disorder whose common features include cardiac defects, palatal anomalies, facial dysmorphism, developmental delay and immune deficiency. "PI4KA is located in the region of chromosome 22 often deleted in 22q11.2 deletion syndrome, one of the most common clinically relevant microdeletions which has variable expressivity." (PMID 25855803, 2015). "No significant hemizygous changes were identified either in PI4KA or in SNAP29, another gene implicated in brain-related phenotypes associated with 22q11.2 deletion syndrome." (PMID 25855803, 2015).
acute myelocytic leukemia (1 paper, 2022). "Remarkably, the PI4KA expression-high group genes were mainly enriched in both acute myelocytic leukemia and chronic myelocytic leukemia pathogenesis pathways." (PMID 36276647, 2022).
anemia (1 paper, 2024). A reduction in the number of red blood cells, the amount of hemoglobin, and/or the volume of packed red blood cells. "The reduction of Pi4ka inhibits myeloid and erythroid cell differentiation in vitro and promotes anemia in vivo through a mechanism involving the deregulation of AKT, MAPK, and JAK-STAT signaling pathways." (PMID 39139819, 2024).
behavioral (1 paper, 2025). "Among the genes present in this interval, CRKL is an excellent candidate for cardiac and renal defects, according to studies in humans and mice, whereas PI4KA could be a candidate for the neurological/behavioral disorder aspects." (PMID 39858619, 2025).
cataract (1 paper, 2024). Partial or complete opacity of the crystalline lens of one or both eyes that decreases visual acuity and eventually results in blindness. "Because mutations in human PI4KA and NF2 cause overlapping neurodevelopmental defects such as hypomyelination and cataracts, PI4KA-related disorders might be driven by defective Hippo signaling as occurs in Neurofibromatosis type II." (PMID 39116228, 2024).
colon adenocarcinoma (1 paper, 2025). "Because TTC7B, FTO, and PI4KA expression is frequently downregulated in many cancers in the TCGA project, including colon adenocarcinoma (COAD), we performed a validation experiment using COAD and paired surgical margin (SM) samples from 105 patients." (PMID 39897037, 2025).
enterovirus infection (1 paper, 2019). "However, PI4KA inhibition does not affect the final replication yield during enterovirus infection (28, –, 30), suggesting that ER-derived ROs may confer a small benefit early in infection but are ultimately expendable for replication." (PMID 31186324, 2019).
lipid metabolism disorders (1 paper, 2023). "Targeted quantitative lipidomics studies confirmed a pathogenic role for variants in genes associated with lipid metabolism disorders, such as PI4KA, PCYT2 and ACER3, in n = 4 cases." (PMID 37679823, 2023).
liver diseases (1 paper, 2014). "There has been growing interest in phosphatidylinositol 4-kinase type IIIα (PI4KA) and its involvement in liver disease." (PMID 24393405, 2014). "In this context, we investigated PI4KA expression in large cohort of liver diseases." (PMID 24393405, 2014). "The analysis of PI4KA expression in various liver diseases may therefore be informative." (PMID 24393405, 2014).
metastatic prostate carcinoma (1 paper, 2023). A carcinoma that arises from the prostate gland and has spread to other anatomic sites. "Among the PI4P kinases, we found that PI4KA highly expressed in the metastatic prostate cancer compared to the matched primary tumors of PC patients." (PMID 37996444, 2023).
metastatic tumor (1 paper, 2023). "We evaluated multiple NCBI datasets and found that PI4KA is significantly associated with metastatic disease, and in therapy resistance disease its expression is associated with neuroendocrine phenotype." (PMID 37996444, 2023). "To determine the impact of PI4KA expression on disease outcome in metastatic hormone sensitive PCa (mHSPC), we performed RNA-sequence analysis on 50 metastatic tumor biopsies, out of which 39 are bone biopsies, 10 lymph node and 1 liver biopsy." (PMID 37996444, 2023). "Here in with analysis of two other data sets (GSE6919 and Ref.35) we show that the level of PI4KA expression correlates with PCa metastatic tumor and neuroendocrine differentiation phenotype." (PMID 37996444, 2023).
neuronal migration disorder (1 paper, 2019). "Mutations in PI4KA have recently been linked to an autosomal recessively inherited neuronal migration disorder." (PMID 30614210, 2019).
osteosarcoma (1 paper, 2011). A usually aggressive malignant bone-forming mesenchymal neoplasm, predominantly affecting adolescents and young adults. "In our previous work, we found that PI4KA silencing led to the formation of NS5A-positive membrane clusters in a U2-OS osteosarcoma cell line model of inducible HCV polyprotein expression." (PMID 22022594, 2011). "We had previously found that PI4KA silencing in U2-OS osteosarcoma cells inducibly expressing a full-length HCV polyprotein led to abnormal NS5A-positive membrane clusters." (PMID 22022594, 2011).
cancer (15 papers, 2018 to 2025). A tumor composed of atypical neoplastic, often pleomorphic cells that invade other tissues. "PI4KA and its regulatory proteins have also been shown to be critical for cancer growth and viral infection." (PMID 39705356, 2024). "Taken together, these findings show that the PI4KA signaling contributes to the growth of cancer cells in bone." (PMID 37996444, 2023). "EFR3A-PI4KA interaction on the PM has been implicated in many KRAS-dependent tumors, and treatments with PI4KA inhibitors along with KRAS inhibitors, or MAPK and PI3K inhibitors have proved to improve efficacy in cancer cell growth inhibition." (PMID 38239314, 2023). "Deeper understanding of PI4KA activation could provide clues for developing newer therapies for targeting the PI signaling in cancer cells." (PMID 38239314, 2023). "We thus suggest that a PI4KA inhibitor may have a therapeutic window in situations whereby oncogenic KRAS signaling is already reduced, rendering cancer cells hypersensitive to any further loss of KRAS signaling." (PMID 34504076, 2021). "The TTC7B protein mainly localizes to the cytoplasm and plasma membrane and physically interacts with PI4KA, which activates several key signaling pathways, including the PI3K/AKT and MEK/ERK pathways, which promote cancer cell proliferation 26-28." (PMID 39897037, 2025). "The finding that EFR3A recruits PI4KA and binds oncogenic KRAS suggests the possibility of targeting this signaling circuit at the level of the kinase for the treatment of KRAS-mutant cancers." (PMID 34504076, 2021). "Considering age, several genes responsible for inflammatory protein secretion/activation (KLK3, EDN3), cell-adhesion (PI4KA, AHSAI1) and cancer-related proteins (KLK3, FGFR1/2, PRKACA, and RAC2) were also modulated in AYA-RMS." (PMID 31533233, 2019). "Some cancers also require EFR3 and PI4KA activity for their aggressive growth." (PMID 39705356, 2024). "Here we show that low doses of the PI4KA-specific inhibitor C7 are synergistic with the clinical KRASG12C-specific inhibitor sotorasib, resulting in near complete ablation of the transformed growth of KRASG12C-mutant human cancer cell lines." (PMID 34504076, 2021).
tumor (8 papers, 2014 to 2024). "Among all the PI4P producing enzymes high tumor PI4KA and PI4K2B expression is associated with poor overall survival in mHSPC patients, whereas the expression of other two PI4P producing enzymes PI4KB and PI4K2A do not have statistical significance." (PMID 37996444, 2023). "Altogether, the tumor expression data suggest PI4KA is associate with aggressive forms of PCa." (PMID 37996444, 2023). "Although the expression of M1 immune-active macrophages were similar between low and high PI4KA biopsies, the presence of M0 and M2 makes the environment more irresponsive to any anti-tumor immune activity." (PMID 37996444, 2023). "High levels of PI4KB, PI4KA, and PI4K2A are associated with a poor prognosis in multiple tumor types and drive malignant progression through distinct mechanisms." (PMID 36757799, 2023). "PI4KA plays a critical role in regulating tumorigenesis by activating tumor-promoting signals such as the RAS pathway." (PMID 36900206, 2023). "The bone met samples were categorized based on median high and low PI4KA expression and heatmaps of this analysis shows a set of genes commonly regulated across the tumor biopsy samples." (PMID 37996444, 2023). "PI4KA could be potentially used as a tumor-intrinsic biomarker for optimizing patient selection and responsive to specific treatment type." (PMID 37996444, 2023). "Through large-scale CRISPRi screening, we discovered genetic modifiers in GBM cells, including ARPC4, PI4KA, ATP6V1A, UBA1, and NDUFV1, that regulated the efficacy of CAR T cell-mediated tumor killing." (PMID 38561797, 2024). "The expression levels of SH3BP1, KDM5B (involved in serine/threonine kinase activity pathway) and PI4KA (belongs to inositol phosphate metabolism pathway) were notably increased in cells overexpressing CPTP, and are associated with tumor progression." (PMID 35982909, 2022).
infection (7 papers, 2010 to 2024). The state of being infected such as from the introduction of a foreign agent such as serum, vaccine, antigenic substance or organism. "EMCV 3A-A32V infection under PI4KA inhibition produced single- and double-membrane cardiovirus ROs (left, white arrowheads and asterisks, respectively), typically in proximity to the ER (black arrowheads)." (PMID 29666283, 2018). "PI4KA inhibition under A1 treatment led to a more clustered, perinuclear dsRNA signal compared to uninhibited infections with EMCV 3A-A32V or wt EMCV." (PMID 29666283, 2018). "In contrast and despite high levels of viral protein being present, the PI4P signal was hardly detected in cells treated with AL-9 throughout the infection with the mutant, likely due to inhibition of PI4KA activity by AL-9." (PMID 27303747, 2016). "Previously, we showed that PI4KA redistributes to EMCV ROs during infection, where it colocalizes with 3A(B)." (PMID 27303747, 2016). "Expression of 3A alone was sufficient for PI4KA recruitment in intact cells, arguing that in infection, PI4KA is recruited to ROs by this viral protein." (PMID 26406250, 2015). "Since PI4P lipids serve to accumulate OSBP and cholesterol at EMCV wt ROs, we next addressed the issue of whether OSBP and cholesterol were present at the ROs of EMCV 3A mutants when PI4KA was inhibited throughout infection." (PMID 27303747, 2016). "We reasoned this could be indicative of a temporal regulation of the PI4KA activity during infection via 3C-dependent degradation." (PMID 26406250, 2015). "To corroborate that PI4KA activity is required for the step of viral genome replication, we performed a time-of-addition experiment in which AL-9 was added to the cells at different time points after infection with RLuc-EMCV." (PMID 26406250, 2015). "To explore this possibility, we performed western blot analysis of endogenous PI4KA during the time course of infection, but did not detect any bands indicative of degradation, neither in Huh7-Lunet/T7 or HeLa R19 cells." (PMID 26406250, 2015). "Cholesterol was redistributed to EMCV ROs upon infection, and treatment with AL-9 or OSW-1 resulted in a significantly reduced colocalization of cholesterol with 3AB, arguing that accumulation of cholesterol at ROs is mediated by both PI4KA and OSBP." (PMID 26406250, 2015).
autosomal recessive disease (1 paper, 2022). Autosomal recessive form of disease. "PI4KA mutations can cause autosomal recessive diseases involving neurological, intestinal, and immunological conditions (OMIM:619621, 616531, 619708)." (PMID 36341355, 2022).
gastrointestinal disorders (1 paper, 2024). "Dysregulation of PI4KA is involved in multiple human diseases, with loss-of-function mutations in PI4KA or its regulatory proteins being causative of neurological, immunological, and gastrointestinal disorders." (PMID 39705356, 2024).
genetic diseases (1 paper, 2022). "With recent advancements in sequencing technology, it has finally been demonstrated that PI4KA gene mutation can cause single-gene recessive genetic diseases." (PMID 36341355, 2022).
PI4KA also shares sentences with these, for which no sentence is quoted: neurodevelopmental disorder (4 papers); acute kidney injury (2); Alzheimer disease (2); dyslipidemia (2); Intellectual disability (2); pancreatic cancer (2); Spastic paraplegia (2); Spasticity (2); asthma (1); autism spectrum disorder (1); autosomal recessive spastic paraplegia-84 (1); brain malformations (1); breast carcinoma (1); cerebellar ataxia (1); chronic myelocytic leukemia (1); cognitive decline (1); Cognitive impairment (1); coloboma (1); colon cancer (1); disorders of iris (1); Dystonia (1); Epileptic encephalopathy (1); Failure to thrive (1); hematological malignancies (1); hereditary spastic paraplegia (1); ichthyosis (1); inflammatory bowel disease (1); insulinoma (1); intestinal atresia (1); intestinal disorder (1).
A further 18 diseases each share a sentence with PI4KA in 1 paper.